FSTL1 (follistatin like 1)
Diseases named in the same sentence as FSTL1 in open-access papers (continued):
Sharing a sentence is not in itself a finding about the gene and the disease.
pulmonary fibrosis (19 papers, 2016 to 2026). Chronic progressive interstitial lung disorder characterized by the replacement of the lung tissue by connective tissue, leading to progressive dyspnea, respiratory failure, or right heart failure. "Fstl1 has been linked to pulmonary fibrosis and inflammation, particularly in experimental arthropathies." (PMID 34502419, 2021). "Previous studies demonstrated that decreased levels of FSTL1 in heterozygous FSTL1+/−-deficient mice attenuated bleomycin-induced pulmonary fibrosis through a TGF-β-dependent pathway." (PMID 28845090, 2017). "However, the mechanisms underlying the detrimental effects of FSTL1 on the progression of pulmonary fibrosis have largely remained elusive." (PMID 38928297, 2024). "Thus, the attenuated lung fibrosis developed in Fstl1+/− mice was associated with a significant decrease in inflammatory cell recruitment." (PMID 28341862, 2017). "Quercetin exerts its protective effects against pulmonary fibrosis by suppressing FSTL1 expression and modulating the NF-κB signaling pathway, thereby inhibiting both inflammation and EMT process." (PMID 40808692, 2025). "In conclusion, this study demonstrates that quercetin, a natural compound, significantly improves the inflammatory response and EMT process in BLM-induced pulmonary fibrosis by suppressing FSTL1 expression and modulating the NF-κB signaling pathway." (PMID 40808692, 2025). "This study therefore investigates quercetin’s capacity to mitigate pulmonary fibrosis through targeted modulation of the FSTL1/NF-κB pathway." (PMID 40808692, 2025). "Although our study demonstrates that quercetin alleviates pulmonary fibrosis through FSTL1-mediated suppression of NF-κB signaling, three key limitations warrant consideration." (PMID 40808692, 2025). "Collectively, these findings highlight FSTL1’s pivotal role in mediating quercetin’s anti-fibrotic effects, offering new perspectives on quercetin’s therapeutic potential in pulmonary fibrosis." (PMID 40808692, 2025). "Studies have found that lung injury induces FSTL1 expression, which promotes myofibroblast accumulation and subsequent fibrosis, while blockade of FSTL1 with a neutralizing antibody can inhibit pulmonary fibrosis in mice." (PMID 33714952, 2021). "The results showed that haplodeficiency of Fstl1 or blockage of Fstl1 with a neutralizing antibody attenuated bleomycin induced lung fibrosis in mice." (PMID 32933544, 2020). "Targeting FSTL1 with a specific antibody in vivo ameliorated bleomycin-induced lung fibrosis in mice, similar to FSTL1 genetic insufficiency in transgenic mice heterozygous for the FSTL1 knockout allele." (PMID 31847129, 2019). "Our results reveal that accumulation of extracellular ADO promotes the process of the fibroblast-to-myofibroblast transition via A2BAR/TGF-β1/Fstl1 signaling in MWCNT-induced lung fibrosis." (PMID 30922349, 2019). "In this study, we confirm the profibrotic function of Fstl1 using a silica model of lung fibrosis and peripheral blood samples from patients with silicosis." (PMID 28341862, 2017). "The attenuated lung fibrosis in Fstl1+/− mice was further demonstrated by decreased collagen accumulation, as determined by hydroxyproline content and Masson’s trichrome staining." (PMID 28341862, 2017). "We found that Fstl1 regulated lung fibrosis of silicosis partially through fibroblast activation and differentiation." (PMID 28341862, 2017). "Targeting deletion of Fstl1 significantly attenuated inflammation and lung fibrosis in mouse model of silicosis." (PMID 28341862, 2017). "After PQ treatment, lung expression of FSTL1 was increased and pulmonary fibrosis exacerbated in miR-21 knockdown and wild-type (WT) mice." (PMID 26758514, 2016). "Western blotting was performed to observe the effect of miR-21 knockdown on FSTL1 protein levels in PQ-induced pulmonary fibrosis." (PMID 26758514, 2016).
pulmonary fibrosis (continued). "To assess effects of RPE in PQ-induced lung fibrosis, we measured miR-21 and FSTL1 gene expression with real-time PCR and p-p38MAPK, NF-kB65, p-Smad2/3 and MMP-9 protein expression with western blotting in lung tissue from mice on day 14 after PQ challenge." (PMID 26758514, 2016). "This suggests that TGF-β1 plays a regulatory role in FSTL1 expression, which may be integral to the pathogenesis of pulmonary fibrosis." (PMID 40808692, 2025). "Treatment with quercetin significantly reduced the fluorescence levels of both FSTL1 and α-SMA, suggesting that quercetin’s regulatory effects on pulmonary fibrosis may involve FSTL1." (PMID 40808692, 2025). "Our research has initially identified FSTL1 as a major pro-fibrotic factor in lung fibrosis." (PMID 39990230, 2025). "Since NF-κB plays a key role in regulating the expression of FSTL1, quercetin may downregulate FSTL1 expression to inhibit pulmonary fibrosis by inhibiting the NF-κB signaling pathway." (PMID 40808692, 2025). "Consequently, this study aims to explore the role of FSTL1 in the EMT process of pulmonary fibrosis and its regulatory mechanisms on the NF-κB pathway, providing a novel perspective on the development of therapeutic strategies for IPF." (PMID 40808692, 2025). "Notably, some of these proteins (e.g., FSTL1) have been demonstrated to exacerbate lung fibrosis by promoting EMT." (PMID 41007698, 2025). "Furthermore, neutralizing antibodies to functionally block FSTL1 and deletion of the FSTL1 gene attenuate bleomycin-induced lung fibrosis in mice." (PMID 38928297, 2024). "In contrast, at baseline FSTL1 production seemed already exhausted in patients with end-stage pulmonary fibrosis developing PGD but could still be temporarily increased by the intraoperative inflammatory response." (PMID 36290379, 2022). "Our data confirm that Fstl1 is up-regulated in response to silica injury and suggested that Fstl1 may play a role in the pathogenesis of silica-induced lung fibrosis." (PMID 28341862, 2017). "Additionally, we provide the in vivo animal evidences to support the therapeutic role of Fstl1 for lung fibrosis." (PMID 28341862, 2017). "Our data suggest that Fstl1 plays an important role in lung fibrosis, and may serve as a novel therapeutic target for treatment of silicosis." (PMID 28341862, 2017). "However, the role of Fstl1 in other types of lung fibrosis and their matched mouse models, such as silicosis and its related silica-induced mouse model, has not been investigated." (PMID 28341862, 2017). "The protocol for continual administration of FSTL1 protein is referred to an earlier study in which FSTL1-neutralizing antibody was given every 3 days to justify the interventional impact of FSTL1 on bleomycin-induced lung fibrosis in C57BL/6 mice." (PMID 28361925, 2017). "In this regard, it may be relevant that the pulmonary fibrosis model examined the systemic haplodepletion of Fstl1, whereas this study examined Fstl1 depletion restricted to a portion of cardiac fibroblasts." (PMID 27234440, 2016). "However, protein expression of FSTL1 was significantly decreased and pulmonary fibrosis was attenuated in the miR-21 knockdown mice, as compared with in WT mice." (PMID 26758514, 2016). "As Fstl1 deletion on myofibroblasts also had antifibrotic effects in the lung, we assessed whether 22B6 mAb administration at day 8, 11, 14, and 17 after intratracheal silica could prevent further progression of lung fibrosis." (PMID 28341862, 2017). "However, the role of FSTL1 in regulating EMT in pulmonary fibrosis remains unclear." (PMID 40808692, 2025). "We have previously shown that FSTL1 is a mesenchymal-derived matricellular protein that is upregulated in lungs from patients of IPF and in bleomycin model of lung fibrosis." (PMID 39990230, 2025). "Quercetin mitigates pulmonary fibrosis by suppressing EMT and inflammation, yet its regulation of FSTL1/NF-κB axis remains unexplored." (PMID 40808692, 2025).
pulmonary fibrosis (continued). "Critically, our study extends this paradigm to pulmonary fibrosis: FSTL1 overexpression in A549 cells amplified NF-κB and cytokines (IL-1β/TNF-α/IL-6), FSTL1 inhibition attenuated TGF-β1-induced inflammation." (PMID 40808692, 2025). "Critically, FSTL1 knockout suppressed EMT markers (α-SMA and N-cadherin), establishing FSTL1 as a pivotal EMT driver in pulmonary fibrosis." (PMID 40808692, 2025). "Follistatin-like-1 (FSTL1) was found to be elevated in serum from patients with silicosis and in mouse lung fibrosis models." (PMID 34439762, 2021). "The number of cells expressing FSTL1 and α-SMA was significantly increased during PQ-induced pulmonary fibrosis and this increase was significantly reduced by RPE treatment." (PMID 26758514, 2016). "In our study, PQ markedly upregulated miR-21 expression, stimulated FSTL1 expression, facilitated TGF-β/Smad2/3 and p38MAPK signal transduction and induced pulmonary fibrosis." (PMID 26758514, 2016). "Expression levels of miR-21, FSTL1, p-p38MAPK, NF-kB65, p-Smad2/3 and MMP-9 in the lung were increased during PQ-induced pulmonary fibrosis." (PMID 26758514, 2016). "In vivo Western blot and qPCR results further demonstrated that FSTL1 expression and the pNF-κB/NF-κB ratio were elevated in the BLM group, suggesting that the FSTL1/NF-κB signaling pathway contributes to the progression of pulmonary fibrosis." (PMID 40808692, 2025). "However, administration of RPE significantly suppressed PQ-induced miR-21 expression, blocked FSTL1 expression, decreased p-p38MAPK, NF-kB65, p-Smad2/3 and MMP-9 protein levels and attenuated pulmonary fibrosis." (PMID 26758514, 2016).
liver fibrosis (18 papers, 2019 to 2025). "FSTL-1 plays a crucial role in liver fibrosis, being its decrease related to the liver damage caused by the acute EtOH ingestion." (PMID 37676577, 2023). "In the genetic models used, we demonstrated that Fstl1-haplodeficiency mice were less susceptible to chemically induced liver fibrosis." (PMID 32933544, 2020). "FSTL-1 also attenuates liver fibrosis, increases endothelial function and revascularization, and improves cardioprotection." (PMID 40507111, 2025). "We induced liver fibrosis in Fstl1+/− mice and treated them with recombinant FSTL1 protein or FSTL1 + PF4136409 before MSC transplantation." (PMID 40050288, 2025). "We propose that FSTL1 is a fibrosis-specific predictor of stem cell-based treatment efficacy in patients with liver fibrosis." (PMID 40050288, 2025). "As described in precancerous lesions of liver cancer, FSTL1 can remodel macrophage function by modulating PKM2 to promote liver fibrosis." (PMID 38605354, 2024). "For instance, CircPWWP2A has been suggested to enhance hepatic stellate cells (HSCs) growth and activation and liver fibrosis by acting as the sponge of miR-203 and miR-223, which then up-regulate Fstl1 and Tlr4, respectively." (PMID 37371520, 2023). "Silencing Fstl1 using shRNA can reduce Col1a1 mRNA expression and macrophage accumulation in carbon tetrachloride injury-mediated liver fibrosis in mice." (PMID 37770480, 2023). "Macrophage FSTL1 has been shown to promote liver fibrosis by inducing M1 polarization and inflammation." (PMID 37770480, 2023). "Based on these findings, we focused on the role of intrinsic FSTL1 in MSCs for the treatment for liver fibrosis." (PMID 35932064, 2022). "To further assess the role of intrinsic FSTL1 in MSCs for their anti-fibrotic efficacy, we transplanted FSTL1low MSCs via tail vein into mice with CCl4-induced liver fibrosis." (PMID 35932064, 2022). "Our data suggest that FSTL1 facilitates the immunosuppression of MSCs on macrophages and guarantee the anti-fibrotic effect of MSCs in liver fibrosis." (PMID 35932064, 2022). "Our data suggest that FSTL1 facilitates the immunosuppression of MSCs on macrophages and guarantees the anti-fibrotic effect of MSCs in liver fibrosis." (PMID 35932064, 2022). "Our data suggest that FSTL1 facilitates the immunosuppression of MSCs on macrophages and that guarantee the anti-fibrotic effect of MSCs in liver fibrosis." (PMID 35932064, 2022). "Haplodeficiency of Fstl1 or blockage of Fstl1 with a neutralizing antibody 22B6 attenuated CCl4-induced liver fibrosis in vivo." (PMID 32933544, 2020). "We found that Fstl1 is evolved in the pathogenesis of liver fibrosis through a TGF-β1-miR29a-Fstl1 regulatory circuit and can serve as a therapeutic target for the treatment of liver fibrosis." (PMID 32933544, 2020). "FSTL1 induces liver fibrosis through hepatic stellate cell activation; CTSB plays key roles in extracellular matrix (ECM) degradation and tissue remodeling, which drive hepatic stellate cell proliferation and promote fibrogenic potential." (PMID 32050622, 2020). "Then we examined the expression of Fstl1 in a well-characterized murine model of CCl4 induced liver fibrosis." (PMID 32933544, 2020). "To determine the role of Fstl1 in vivo, we subjected Fstl1+/− and littermate wild type (WT) mice to the CCl4 induced liver fibrosis." (PMID 32933544, 2020). "Here, we provide evidence that targeting Fstl1 inhibits the activation of HSCs and ameliorates CCl4-induced liver fibrosis in mice by modulating TGF-β1-miR29a-Fstl1 regulatory circuit and downstream Smad2/JNK signaling in activated HSCs." (PMID 32933544, 2020). "In this study, we aim to analyze the role of Fstl1 in liver fibrosis by using TGF-β1 activated HSCs in vitro and a mouse model of CCl4-induced liver fibrosis." (PMID 32933544, 2020).
liver fibrosis (continued). "Hepatic stellate cell (HSC) line LX-2 stimulated by TGF-β1, primary culture of mouse HSCs and a model of liver fibrosis induced by CCl4 in mice was used to assess the effect of Fstl1 in vitro and in vivo." (PMID 32933544, 2020). "To this end, we aimed to study whether host FSTL1 affects the therapeutic efficacy of stem cells in liver fibrosis by modulating the fibrotic microenvironment in which stem cells are exposed." (PMID 40050288, 2025). "FSTL1 acts as a pro-fibrotic factor in organs, including the liver, in the case of liver fibrosis." (PMID 35932064, 2022). "Further studies are needed to determine whether Fstl1 modulates inflammatory responses in liver fibrosis." (PMID 32933544, 2020). "Fstl1 may serve as a novel therapeutic approach in the treatment for patients with severe liver fibrosis." (PMID 32933544, 2020). "Thus, Fstl1 signaling inhibited miR29a expression in HSCs in vitro and in liver fibrosis induced by CCl4 in vivo." (PMID 32933544, 2020). "Then we examined whether Fstl1 neutralizing antibody (22B6 mAb) would ameliorate CCl4-induced liver fibrosis in vivo, we treated Babl/c mice with 22B6 mAb or IgG1 along with CCl4 treatment." (PMID 32933544, 2020). "Our observation also confirmed the previous studies that knockdown Fstl1 attenuate liver fibrosis." (PMID 32933544, 2020). "Fstl1+/− mice also showed reduced degree of liver fibrosis, as determined by Sirius-red staining." (PMID 32933544, 2020). "Furthermore, we demonstrated that there was a TGF-β1-miR29a-Fstl1 regulatory circuit mediating liver fibrosis." (PMID 32933544, 2020). "This work highlights the importance of Fstl1 in liver fibrosis." (PMID 32933544, 2020). "Our results support the hypothesis that 4MU alleviates CCl4-induced liver fibrosis by reducing hyaluronan deposition and downregulating FSTL1 expression, accompanied by the suppression of HSC trans-differentiation and altered macrophage localization." (PMID 31847129, 2019). "FSTL1 came out of the comparative screen of the genes activated in renal and liver fibrosis." (PMID 31847129, 2019). "Thus, we deduced that Fstl1 neutralizing antibody could attenuate CCl4-induced liver fibrosis in mice through blocking phosphorylation of Smad2/JNK." (PMID 32933544, 2020). "So Fstl1 may also act on endothelial cells or other cell types in liver fibrosis." (PMID 32933544, 2020). "Further mechanistic studies demonstrate that CircPWWP2A promotes HSC growth and activation as a sponge of miR-203 and miR-223, which then promotes Fstl1 and TLR4 levels, respectively, and eventually promotes liver fibrosis." (PMID 37371520, 2023). "Macrophages follistatin-like protein 1 (FSTL1) binds to PKM2, induces M1 polarization and inflammation, and promotes the progression of liver fibrosis." (PMID 37663261, 2023). "In the present study, we knocked down FSTL1 in MSCs and observed the abolishment of MSC-mediated anti-fibrotic therapy in carbon tetrachloride (CCl4)-induced liver fibrosis." (PMID 35932064, 2022). "Here, we tried to determine the role of FSTL1 in MSC therapy and investigate how it affects the treatment outcome in liver fibrosis." (PMID 35932064, 2022). "Consistent with the results of MSC-based therapy, we also found that MNCs significantly ameliorated liver fibrosis in wild-type mice but showed no functional benefit on liver fibrosis in Fstl1+/− mice." (PMID 40050288, 2025). "The data indicated that endogenous FSTL1 expression in MSCs is indispensable for MSC treatment outcomes in liver fibrosis without a tendency to promote fibrogenesis." (PMID 35932064, 2022). "Our data suggests TGF-β1-miR29a-Fstl1 regulatory circuit plays a key role in regulation the HSC activation and ECM production, and targeting Fstl1 may be a strategy for the treatment of liver fibrosis." (PMID 32933544, 2020). "Then we explored the relationship among Fstl1, miR29a, and TGF-β1 in liver fibrosis." (PMID 32933544, 2020).
liver fibrosis (continued). "As the smallest member in the Fst-SPARC family, the role of Fstl1 in liver fibrosis and its therapeutic potential has not been fully investigated." (PMID 32933544, 2020).